DARS1 (aspartyl-tRNA synthetase 1)
Description:
Catalyzes the specific attachment of an amino acid to its cognate tRNA in a 2 step reaction: the amino acid (AA) is first activated by ATP to form AA-AMP and then transferred to the acceptor end of the tRNA.
Synonyms: AspRS; DARS; HBSL
Tractability: PROTAC: ubiquitination databases record sites on it.
Target class: Enzyme; Ligase
Gene: Protein-coding gene on chromosome 2 (135,905,881 to 135,986,100, reverse strand). Ensembl gene ENSG00000115866.
Subcellular location: Cytoplasm, cytosol
Subcellular location (Human Protein Atlas): Cytosol
Pathways (Reactome):
Developmental Biology: Transcriptional and post-translational regulation of MITF-M expression and activity
Metabolism: Selenoamino acid metabolism
Metabolism of proteins: Cytosolic tRNA aminoacylation
Gene Ontology:
Molecular function: aspartate-tRNA ligase activity; protein binding; RNA binding; aminoacylase activity; aminoacyl-tRNA ligase activity; ATP binding; nucleic acid binding; nucleotide binding
Biological process: aspartyl-tRNA aminoacylation; protein-containing complex assembly; translation; tRNA aminoacylation for protein translation
Cellular component: aminoacyl-tRNA synthetase multienzyme complex; cytosol; extracellular exosome; membrane; cytoplasm; synapse
Genetic constraint (gnomAD): Loss-of-function variants: 22 observed, 30.72 expected, observed/expected ratio (o/e) 0.72, 90% interval 0.51 to 1.02. The upper end of that interval is the gene's LOEUF score, 1.02, which puts it in group 4 of 6, group 1 being the genes least tolerant of losing a copy. Missense variants: 264 observed, 309.42 expected, observed/expected ratio (o/e) 0.85, 90% interval 0.77 to 0.94. Synonymous variants: 98 observed, 102.65 expected, observed/expected ratio (o/e) 0.95, 90% interval 0.81 to 1.13.
Homologues: Orthologues: macaque DARS1 (99% identical), chimpanzee DARS1 (99% identical), dog DARS1 (97% identical), guinea pig DARS1 (96% identical), mouse Dars1 (96% identical), rabbit DARS1 (93% identical), pig DARS1 (91% identical), tropical clawed frog dars1 (88% identical), zebrafish dars1 (83% identical), Drosophila melanogaster AspRS (67% identical), Caenorhabditis elegans dars-1 (63% identical). Paralogues in human: NARS1 (26% identical), DARS2 (23% identical), NARS2 (23% identical), KARS1 (22% identical).
Diseases named in the same sentence as DARS1 in open-access papers:
DARS1 is named in the same sentence as 39 diseases in open-access papers, as found by Europe PMC text mining. Sharing a sentence is not in itself a finding about the gene and the disease. The quoted sentences say what the papers report.
leukodystrophy (3 papers, 2018 to 2022). Leukodystrophies are a group of rare, progressive, metabolic, genetic diseases that affect the brain, spinal cord and often the peripheral nerves. "The leukodystrophy Hypomyelination with Brainstem and Spinal cord involvement and Leg spasticity (HBSL) is caused by recessive mutations of the DARS1 gene, which encodes the cytoplasmic aspartyl-tRNA synthetase." (PMID 35357600, 2022). "Accurate animal models of the leukodystrophy HBSL have been challenging to establish in the past, as Dars1 mutations have either resulted in severe developmental deficits and premature death or failed to trigger HBSL pathology altogether." (PMID 35357600, 2022).
developmental delay (1 paper, 2022). "Compound heterozygous Dars1M256L/− mice carrying the hypomorphic Dars1M256L mutation in trans to a Dars1-null allele presented with severe developmental delay, spinal cord white matter vacuolization and reduction of myelin markers in the hindbrain." (PMID 35357600, 2022).
Hydrocephalus (1 paper, 2022). Hydrocephalus is an active distension of the ventricular system of the brain resulting from inadequate passage of CSF from its point of production within the cerebral ventricles to its point of absorption into the systemic circulation. "Homozygous Dars1 knockout is embryonically lethal, while mice carrying a hypomorphic Dars1D367Y allele in trans to a deletion allele present with early developmental delay, hydrocephalus, hypomyelination and white matter vacuolization, followed by late onset motor impairment." (PMID 35357600, 2022).
Parkinson's (1 paper, 2025). "We are not aware of any existing evidence for the role of DARS1 in Parkinson's pathogenesis, but its identification by COWAS points to a potential avenue for further research." (PMID 39711708, 2025).
tumor (5 papers, 2021 to 2025). "Studies have indicated that DARS1 is upregulated in several cancers, including TNBC, where it supports tumor growth and survival." (PMID 40867231, 2025).
cancer (4 papers, 2021 to 2025). A tumor composed of atypical neoplastic, often pleomorphic cells that invade other tissues. "However, there is not enough evidence in the literature that associates DARS1 (DARS) gene to different cancers." (PMID 34249670, 2021). "The disruption of ARSs, including DARS1, IARS1, and KARS1, has been associated with cancer progression." (PMID 40867231, 2025).
neurological disorder (4 papers, 2021 to 2024). "Further, we tested aspartyl-tRNA synthetase (DARS1), which is associated with a recessive neurological disorder characterized by hypomyelination, brain stem and spinal cord abnormalities, and leg spasticity." (PMID 36890170, 2023).
infection (3 papers, 2014 to 2021). The state of being infected such as from the introduction of a foreign agent such as serum, vaccine, antigenic substance or organism. "Interestingly, the level of cAMP and the phosphorylation of Cmk1 in DARS1 was higher than that in the DARS2; however, the pathogenicity of DARS1 was not attenuated during the infection of cucumber leaves." (PMID 25275394, 2014).
DARS1 also shares sentences with these, for which no sentence is quoted: Leukoencephalopathy (6 papers); Ataxia (2); breast cancer (2); Cognitive impairment (2); colorectal cancer (2); hypomyelination with brain stem and spinal cord involvement and leg spasticity (2); acute myeloid leukemia (1); Alexander disease (1); biotinidase deficiency (1); bladder cancer (1); cerebellar ataxia (1); colon adenocarcinoma (1); colon cancer (1); Encephalopathy (1); glioblastoma (1); hypomyelinating leukodystrophy 9 (1); intellectual disabilities (1); liver cancer (1); lung adenocarcinoma (1); lung carcinoma (1); lung squamous cell carcinoma (1); microcephaly (1); neoplasm of central nervous system (1); neoplasm of the nervous system (1); pituitary adenoma (1); pituitary tumor (1); prostate adenocarcinoma (1); renal cell carcinoma (1); Sjogren syndrome (1); uterine corpus endometrial carcinoma (1).
A further 1 disease shares a sentence with DARS1 in 1 paper.